MEN1 (menin 1)
Diseases named in the same sentence as MEN1 in open-access papers (continued):
Sharing a sentence is not in itself a finding about the gene and the disease.
tumor (continued). "MEN1 results from a mutation of the MEN1 gene on chromosome 11q13, which acts as a tumor suppressor gene." (PMID 37623030, 2023). "In PDAC, on the other hand, MEN1 is rarely mutated and seems to play a less important role in tumor development." (PMID 37659057, 2023). "MEN1 loss is the most common mutation in PanNETs and has been connected to tumor initiation and progression." (PMID 37270586, 2023). "By constructing a mouse xenograft model, the researchers administered leflunomide to MEN1 mutation‐associated tumors and showed a significant reduction in tumor size." (PMID 36925702, 2023). "Menin has classically been described as a tumor suppressor, where germline inactivating variants in MEN1 promote the development of tumors in the pituitary, parathyroid, and endocrine pancreas leading to multiple endocrine neoplasia type 1 (MEN1) syndrome." (PMID 37627154, 2023). "The MEN1 tumor suppressor gene encodes menin, a nuclear protein that has been shown to function as a scaffold protein involved in broad control of transcriptional regulation, including important epigenetic effects." (PMID 36782257, 2023). "Instead, when the decision is between doubly mutated tumor samples, the assignment is almost equally distributed with a slight preference on MEN1 mutated samples." (PMID 37270586, 2023). "In patients with multiple tumors, menin loss in at least one tumor was seen in 100% of 8 patients with MEN1 and 21% of patients with 14 non-MEN1." (PMID 37199453, 2023). "As the previous studies examined the structural effects of MEN1 mutations and the germline variant in a Men1-null murine stromal cell line, we next tested menin turnover in menin competent tumor cell lines." (PMID 37492626, 2023). "MEN1 is an autosomal dominant endocrine neoplasia syndrome characterized by a high risk of neoplasia in the endocrine organs." (PMID 35698198, 2022). "We demonstrated that increased hTS expression was associated with earlier tumor onset and accelerated PanNET development in comparison with control Men1–/– and Men1+/ΔN3-8 mice." (PMID 36048542, 2022). "MEN1 mutations can be found in almost half of PanNET tumors, underlying its substantial involvement in tumor development." (PMID 35163032, 2022). "Men1 loss is known to downregulate p18INK4c and p27Kip1, which promotes cell cycle progression and tumor development in islet cell tissues." (PMID 36048542, 2022). "In this case, a 44-year-old woman followed for de novo MEN1 presented with memory loss and disorientation and was found to have a large tumor causing obstructive hydrocephalus, a tumor that ultimately led to her death." (PMID 36325452, 2022). "In these patients, the coexistence of germline mutations and loss of heterozygosity (LOH) in tumor tissue for tumorigenesis demonstrates that the MEN1 gene acts as a classic tumor suppressor." (PMID 34711954, 2022). "MEN1 gene mutations cause a hereditary autosomal dominant tumor syndrome (MEN1 syndrome), leading to tumor formation in multiple endocrine organs." (PMID 34711954, 2022). "Due to this variability of tumour development, MEN1 mutation carriers are advised to undergo DNA testing, genetic counselling and regular screening for tumours, from as young as 5 years of age." (PMID 35900839, 2022). "These patients are then generally subject to specific routine MEN1-associated tumour follow-up protocols, using regular biochemical markers and imaging procedures." (PMID 36694894, 2022). "The MEN1 gene acts as a classic tumor suppressor gene in endocrine tissues: loss of function results in tumorigenesis." (PMID 35941657, 2022). "A role for miRNAs in the regulation of menin expression and in the development of MEN1-associated tumours has previously been reported." (PMID 35900839, 2022). "These somatic mutations observed in 5-month-old hTS/Men1–/–/BB mice due to TS overexpression correlate with the accelerated tumor progression found in age-matched hTS/Men1–/– mice." (PMID 36048542, 2022).
tumor (continued). "Tumor formation in Men1 mouse models is delayed even with biallelic loss of Men1 in β-cells, making these animals less than optimal for drug efficacy testing." (PMID 34680266, 2021). "The tumor suppressor menin, encoded by the MEN1 gene can act as either a tumor suppressor or an oncogene/oncoprotein, depending on the oncological context." (PMID 34356858, 2021). "Prolonged tumor latency in these mice suggests that additional genetic alterations cooperate with Men1 loss to drive pNET development." (PMID 34680266, 2021). "Tumor-associated frameshift and nonsense mutations in MEN1 encode truncated forms of the protein that lack one or both NLS and protein-protein interaction domains." (PMID 34680266, 2021). "In MEN1 disorder, for example, menin acts as a tumor suppressor as loss-of-function mutations in the MEN1 gene are responsible for tumor developments of more than 95% of MEN1 patients." (PMID 34356858, 2021). "PDX1 presented hypermethylation and lower expression in tumours with mutations in the ATRX/DAXX/MEN1 genes (T2 and T3) than in wild-type tumours (T1)." (PMID 33536587, 2021). "Despite its rare occurrence, thymic carcinoid tumor should be considered as a MEN1-associated tumor and necessitates screening of other endocrine glands." (PMID 33632163, 2021). "As a tumor suppressor gene, the MEN1 gene functions mainly as loss of heterozygosity at the menin locus of chromosome 11q13, and present genetic testing for the MEN1 gene focuses on detection of the polymorphic markers in this region." (PMID 34160414, 2021). "Menin, the protein product encoded by the MEN1 gene, has been extensively studied for its role as a tumour suppressor." (PMID 34943798, 2021). "MEN1 was early on assigned a tumor-suppressor gene status, as the bulk of mutational events in MEN1 kindred reported represent inactivating events leading to premature truncations of the menin protein." (PMID 33269427, 2021). "The lack of knowledge of its pathogenesis limits the ability to explore therapies directed at this tumor, which is the most aggressive of all MEN1-associated tumors." (PMID 34515662, 2021). "Generally, the MEN1-related tumors occurrence requires inheritance of a germline mutation of MEN1 gene together with a somatic mutation in the DNA of tumor, leading to LOH, according to the two hits model by Knudsons’." (PMID 33312161, 2020). "Several Men1 mouse models generated by targeted mutation of the Men1 gene effectively mimic the tumor spectrum in humans." (PMID 32733644, 2020). "Germline heterozygous mutation in the MEN1 tumor suppressor gene encoding menin predisposed to tumor development." (PMID 33204258, 2020). "The prolonged latency of tumor development in MEN1 patients suggests a likelihood that other mutations cooperate with Men1 to induce PanNETs." (PMID 31160716, 2020). "The first hit leads to MEN1 gene heterozygous mutation of genital cells, and the second hit was certain chromosome deletion of somatic or tumor cells." (PMID 32126984, 2020). "MEN1-associated tumours show a loss of heterozygosity of the MEN1 gene, which is located on chromosome 11q13 and encodes the ubiquitously expressed, predominantly nuclear scaffold tumour-suppressor protein, menin." (PMID 32348957, 2020). "MEN1 is a tumor suppressor gene, and mutations that disrupts MEN1 function are common to many tumor types." (PMID 32937789, 2020). "Although germline MEN1 mutations contribute to the clinical pathologies of the parathyroid, thyroid, and pancreatic syndromes, we find that very few contribute to neoplasia and cancer." (PMID 32937789, 2020). "Peculiarly, patients with mutations that affect the JunD-interacting domain have a higher risk of death for a typical MEN1 tumor, requiring a more aggressive therapeutic approach." (PMID 33312161, 2020). "Typically, tumour development is associated with the mutation of both MEN-1 alleles, however, an incomplete inactivation of this gene has been observed in thymic and duodenal NETs." (PMID 31443481, 2019).
tumor (continued). "As reported, MEN1 gene encodes for menin that act as tumor suppressor, as confirmed by microsatellite analysis conducted on cancerous tissues of MEN1 patients." (PMID 31249555, 2019). "NGS testing should be considered in specific patients with this combination of neoplasms, as certain germline variants beyond MEN1, have important implications for cancer surveillance." (PMID 31592449, 2019). "MEN1-associated neoplasms were diagnosed as early as within the first 5 years of life, though the majority were diagnosed after the age of 10 with increasing disease penetrance with age." (PMID 31263451, 2019). "It is inherited as an autosomal dominant disease caused by mutations or cytogenetic alterations involving the MEN1 gene, which is a tumour suppressor gene located on chromosome 11q13 that encodes for a protein named menin." (PMID 31482957, 2019). "Other MEN1-associated NETs are thoracic carcinoids, of the thymus and the bronchopulmonary tract, in 3% of cases, and tumours/lesions of the adrenal glands in about 20–40% of patients." (PMID 30428914, 2018). "The majority of mutations in ATRX, DAXX, and MEN1 were truncation mutations (stopgain or frameshift) and loss of function consistent with their role as tumor suppressors." (PMID 30315258, 2018). "- The familial criterion: occurrence of at least one MEN1 associated tumor and a first-degree relative with MEN1." (PMID 30254610, 2018). "Nine patients died (6.21% of affected patients) because of MEN1-related causes and malignant progression of MEN1 tumours." (PMID 30428914, 2018). "The most prevalent primary tumor variants were in the MEN1 (42%), DAXX (11%), ATRX (10%), and TSC2 (8%) genes." (PMID 29212165, 2017). "A tumor harboring a MEN1 variant was a smaller sized lesion when compared to MEN1 WT lesions: 15.9 ± 12.5 mm vs. 24.0 ± 21.1mm; p=0.0377." (PMID 29212165, 2017). "Considerable phenotypic variability of tumor type manifestations and age at diagnosis has been reported, even within the same family, whose affected members share the same, inherited,MEN1 gene mutation." (PMID 28184288, 2017). "Genotyping revealed that the majority of the primary tumor variants were identified in MEN1 (42.2%), DAXX (11.1%), ATRX (10%), and TSC2 (7.8%) genes." (PMID 29212165, 2017). "We did not observed any correlation between SSAs-induced cell viability inhibition and the presence of MEN1 tumor mutations or PTEN, DAXX/ATRX expression levels." (PMID 28454119, 2017). "MEN1 associated pNETs usually present as multiple microadenomas, with some associated larger tumours which are frequently found incidentally or during screening." (PMID 28965289, 2017). "The MEN1 gene is located on chromosome 11q13 and encodes the 610-amino acid menin protein that belongs to the class of tumor suppressors." (PMID 28663159, 2017). "We found an association between the location of MEN1 mutations and the occurrence of specific tumor types." (PMID 29036195, 2017). "The MEN1 (Multiple Endocrine Neoplasia Type 1) gene, which encodes the protein menin, is a tumor suppressor that has been well conserved across evolution." (PMID 27538741, 2016). "Patients with MEN1 are predisposed to developing tumors of the parathyroid, pancreas and pituitary gland." (PMID 25663877, 2015). "The lost region on CFA18 was associated with solid growth and invasive growth into tumour stroma included the MEN1 gene." (PMID 25955013, 2015). "Familial MEN1 is defined by the presence of at least one MEN1-related NET plus at least one-first-degree relative with just one of the three classical tumours or a known MEN1 germline mutation." (PMID 25824098, 2015). "The polymorphism in MEN1 patients was as frequent as other types of tumours, whereas it was significantly different from healthy controls." (PMID 25824098, 2015).
tumor (continued). "MEN1 encodes a nuclear protein Menin, a tumor suppressor which acts as an adapter and interacts with partner proteins involved in crucial activities like transcriptional regulation, cell division, proliferation and genome stability." (PMID 26307114, 2015). "Antagonizing β-catenin signalling by the small molecule inhibitor PKF115-584 in Men1-deficient PNETs suppresses tumour cell proliferation in vitro and in vivo." (PMID 25517963, 2014). "All together, these findings suggest that the ablation of β-catenin in Men1-deficient PNETs inhibits tumorigenesis and tumour growth." (PMID 25517963, 2014). "MEN1 germline mutational analysis should be considered in those presenting at an early age with a single, apparently sporadic MEN1-associated tumor." (PMID 23933118, 2014). "As with MEN-1, this germline mutation is thought to have a high penetration rate, and often involves multiple additional tumor sites including endometrial, ovarian, stomach, small bowel, and ureter carcinoma." (PMID 24910640, 2014). "Lymnaea MEN1 (L-MEN1) encodes the transcription factor menin, a tumor suppressor mutated in humans with MEN1 syndrome, a disorder characterized by tumors of the endocrine organs." (PMID 25347295, 2014). "Targeting β-catenin signalling by a molecular antagonist or a genetic approach significantly inhibits the proliferation of MEN1-deficient tumours." (PMID 25517963, 2014). "Most (75%) of the MEN1 mutations are inactivating and are consistent with those expected in a tumor-suppressor gene." (PMID 23933118, 2014). "The mRNA and protein levels of the pivotal proliferative genes in Men1-deficient tumour cells were significantly downregulated by the β-catenin antagonist." (PMID 25517963, 2014). "Our results reveal that the elevated expression of several proliferative factors, including Mcms, cyclin proteins and Pbk, can be rescued by β-catenin signalling suppression in MEN1-deficient tumours." (PMID 25517963, 2014). "LOH and immunohistochemistry analysis of tumor samples in a heterozygous Men1 knock out mouse model also demonstrated loss of the wild type Men1 allele and absence of menin protein expression in tumor cells." (PMID 25132853, 2014). "The inhibition of β-catenin resulted in the downregulation of key proliferative genes in Men1-deficient tumours." (PMID 25517963, 2014). "The development of potent therapeutic approaches for MEN1-deficient tumours is the greatest challenge in reducing the morbidity and mortality of patients with PNETs." (PMID 25517963, 2014). "The tumor suppressor function of menin was supported when germline inactivating mutations of MEN1 were found in MEN1 cases." (PMID 25132853, 2014). "It is widely believed that MEN1 is a tumour suppressor gene, given that loss of the gene results in formation of tumours as in MEN1 syndrome." (PMID 25309600, 2014). "In MEN-1 the heterozygous germ line mutations of the MEN-1 gene, a tumour-suppressor gene, are by themselves insufficient for tumour development." (PMID 24213225, 2012). "Our previous experiments have indicated that compound heterozygous loss of both Men1 and Rb1 genes has little effect on the rate, severity or onset of tumorigenesis, or on the spectrum of observed tumour types compared to individual gene deletions." (PMID 22708734, 2012). "Both spontaneous and familial cases of human MEN1 mutation result in predisposition to a range of tumour types, predominantly in endocrine organs such as parathyroid, pituitary and enteropancreatic sites." (PMID 22708734, 2012).
tumor (continued). "In the adrenal, we observed development of cortical tumours in dual heterozygous animals, as we have previously seen in Men1+/− animals, and there was loss of heterozygosity at the Men1 allele in these tumours." (PMID 22708734, 2012). "Germline mutations leading to loss of heterozygosity in the tumour suppressor genes MEN1 (menin) and CDC73 (formerly HRPT2) combined with a second mutation in somatic cells can increase the predisposition to parathyroid tumours." (PMID 21747852, 2011). "Menin, a tumor suppressor encoded by the MEN1 gene, has been shown to directly interact with the extreme N-terminus of MLL, and this interaction is essential for MLL-rearranged leukemogenesis." (PMID 21037944, 2010). "A wide variability of tumour occurrence and clinical behaviour, even in patients sharing the same MEN1 mutation, has been described, making it difficult to foresee the clinical phenotype in asymptomatic mutant gene carriers." (PMID 17014705, 2006). "The gene locus causing MEN1 has been localised to chromosome 11q13 by studies of loss of heterozigosity (LOH) on MEN1-associated tumours and by linkage analysis in MEN1 families." (PMID 17014705, 2006). "Thus, while MEN1 is clearly linked to the development of pancreatic and lung NETs, its precise role in tumor aggressiveness across different anatomical sites and its molecular mechanisms require further investigation." (PMID 40026252, 2025). "A role for microRNAs in MEN1-associated tumor initiation and development has been documented." (PMID 40507887, 2025). "However, MEN1-related TNETs show fewer 11q13 losses compared to pancreatic or parathyroid MEN1-associated neoplasms, indicating a distinct tumorigenic pathway." (PMID 40563625, 2025). "Given the established role of MEN1 as a tumor suppressor, these mutations may indicate a potential link to increased immunogenicity or altered signaling pathways that sensitize tumors to ICB." (PMID 40372586, 2025). "Except for one patient with MEN1-associated VIPoma, the other 11 tumours were sporadic." (PMID 39122816, 2024). "Consequently, mutations in MEN1 have a multifaceted impact on a wide range of essential cellular processes, thereby highlighting the tumor suppressor role of the protein." (PMID 39456803, 2024). "MEN1 is the most commonly mutated gene and a typical tumor suppressor in PanNETs." (PMID 39041891, 2024). "In cells with Enhancer of zeste homolog 2 (EZH2) gain-of-function mutations, combinatorial inhibition of MEN1 using MI-503 or VTP50469 with EZH2 inhibitor Tazemetostat (EPZ-6438) has been shown to decrease tumor burden and survivability in a lymphoma xenograft model." (PMID 38279330, 2024). "This is particularly relevant in the case of PNET because PNETs have a low tumor mutational burden and are considered an epigenetic disorder due to the fact that multiple high-frequency mutations, including MEN1, DAXX, and ATRX, are all found involved in epigenetic regulation." (PMID 38279330, 2024). "The diagnosis of MEN1 is complex, dependent on either the identification of two or more MEN1-associated tumors, finding a MEN1 tumor in a patient with a first-degree relative who has a MEN1 pathogenic variant, or uncovering an asymptomatic carrier via genetic cascade screening." (PMID 39104820, 2024). "In synthesis, after the first inherited germinal “hit”, the onset and progression of MEN1-associated neoplasms, including those involving parathyroids, could depend on an impairment of the ‘‘negative feedback loop’’ between menin and miR-24-1." (PMID 39519139, 2024). "However, the index case features a functional ACTH-producing pancreatic-SCNEC (P-SCNEC), a rarity in MEN1-associated NETs, suggesting potential tumor grade progression from a well-differentiated DP-NET." (PMID 39104820, 2024). "Therefore, the normal cells will have both wild-type and mutant alleles of the MEN1 gene, and the tumor cells, which exhibit LOH (90%), will contain the mutant allele only." (PMID 39194755, 2024).